IL6 (interleukin 6)
Diseases named in the same sentence as IL6 in open-access papers (continued):
Sharing a sentence is not in itself a finding about the gene and the disease.
tumor (continued). "Persistent activation of NF-κB and IL-6/STAT3 signaling modifies splicing patterns, increases proteostatic burden, and upregulates ribosome biogenesis, thereby reinforcing the chronic microinflammatory state that promotes tumor initiation and progression." (PMID 41514860, 2025). "Additionally, cytokines such as IL-6, IL-8, IL-10, TNF-α, and TGF-β demonstrate context-dependent activities, intricately regulating immune responses, tumor growth, and metastasis." (PMID 40909271, 2025). "In parallel, IMiDs, including thalidomide, lenalidomide, and pomalidomide, are also considered immunotherapeutic agents due to their capacity to stimulate T and NK lymphocytes, inhibit angiogenesis, and modulate cytokine secretion (e.g., IL-6 and TNF-α) that drives tumor proliferation." (PMID 41471085, 2025). "LIF levels were markedly elevated in the C26 tumor milieu, whereas other known wasting factors (IL-6, TNF-α, myostatin) were not, indicating that LIF is the key wasting cytokine in this model." (PMID 40869331, 2025). "IHC staining was performed for eight cytokine proteins—TNF-α, IFN-γ, TGF-β1, IL-1α, IL-1β, IL-2, IL-6, and IL-12—in paired PeCa tumour samples and corresponding negative-margin tissue." (PMID 41465261, 2025). "Success markers include transient serum cytokine elevations (IL-6, IL-1β), improved tumor CD8+/Treg ratios, and conversion from non-inflamed to inflamed gene signatures in biopsies." (PMID 40227782, 2025). "In both genotypes (WT and KO) and treatment groups (Veh and Bc), CD163+ Toe-Macs were detected within tumor regions expressing high levels of NLRP3, IL-1β, TGF-β1, CCL2, IL-6, and PD-L1." (PMID 40794443, 2025). "Additionally, trabectedin inhibits the production of specific inflammatory mediators in macrophages, such as IL-6 and C-C motif ligand 2 (CCL2), which likely contributes to the depletion of the TAM pool in the tumor microenvironment." (PMID 40918451, 2025). "Emerging evidence demonstrates that CAFs not only respond to oncogenic signals but also actively drive tumor progression through paracrine factor secretion (e.g., TGF-β, IL-6) and extracellular matrix remodeling, and act as critical collaborators in hepatocarcinogenesis." (PMID 40755769, 2025). "Keep an eye on how important things in tumor-derived exosomes move about, including whether inflammatory substances like MIF and IL-6 can get across the vascular barrier and affect cardiomyocytes or cardiac immune cells, and so on." (PMID 40842994, 2025). "Chronic inflammation and oxidative stress induced by prolonged hypertension contribute to vascular endothelial dysfunction, increased ROS, and elevated pro‐inflammatory cytokines such as IL‐6, TNF‐α, and NF‐κB, which can lead to DNA damage and tumor progression." (PMID 40387523, 2025). "Notably, NEU synergistically promotes tumor progression: In the tumor microenvironment (TME), cytokines (TGF-β, IL-8, IL-6, IL-17) drive NEU polarization into the N2 phenotype." (PMID 41357195, 2025). "Furthermore, the abnormal secretion of inflammatory factors (such as IL-6 and TNF-α) from adipose tissue in women with GDM can create a tumor-promoting microenvironment." (PMID 40678319, 2025). "Among the proteomic markers, elevated levels of serum ceruloplasmin, MYO1B, salivary CPLANE1, serum albumin, HSP 27, gamma actin, SCC 1, and A4, serum SNCG and SCCAg and immune cell markers such as, IL‐6, TNF‐α, and CD4 + T cell were suitable proteomic tumor markers in detecting OSCC." (PMID 40256126, 2025). "IL‐6 levels were not significantly different between K and KL mice at early stages, but increased at day 28 when compared to tumour‐free mice." (PMID 40702652, 2025). "In ENKTCL, MSCs may protect tumor cells from apoptosis by secreting soluble anti-apoptotic factors (e.g., IL-6, CXCL12), altering drug metabolism in the LME and physically shielding tumor cells through the formation of protective stromal niches." (PMID 41303704, 2025).
tumor (continued). "Additionally, MDSCs in HR+ BC can secrete cytokines, IL-6, and chemokine ligands (CCLs) like CCL2, suppressing T-cell function and recruiting more immune-suppressive cells to the TME, reinforcing the cold tumor phenotype." (PMID 40281554, 2025). "Analogous immunopathological patterns have been documented in breast malignancies, wherein IL-17A orchestrates a pro-tumorigenic cytokine-chemokine cascade—including IL-6, TGF-β, IL-1 isoforms, IL-8, TNF ligands, CXCL1, and CCL2—to reinforce a tumour-supportive stromal niche." (PMID 40943351, 2025). "IL-6 activates several signaling pathways, including JAK/STAT, MAPK and PI3K pathway, leading to the release of negative regulator suppressor of cytokine signaling 3 (SOCS3) and various pro-tumor molecules." (PMID 40248695, 2025). "Recent studies have demonstrated that lactylation drives the downregulation of retinoic acid receptor gamma (RARγ) in TAMs, thereby enhancing IL‐6 levels in the TME and promoting tumor growth and proliferation through the activation of STAT3 signaling in colorectal tumor cells." (PMID 40443721, 2025). "Apparently, the use of anti-IL-6 antibodies is not enoughto block tumor growth, although monotherapy improves the quality of life ofpatients." (PMID 40264585, 2025). "In metastatic lung cancer, both primary-tumor-released factors, such as MMPs and exosomes, and CAF-secreted proinflammatory cytokines, such as TGF β1, IL-6, and IL-8, were found to enhance the formation of a premetastatic niche that helped lung metastasis of liver cancer." (PMID 40805183, 2025). "Additionally, senescent immune system promotes chronic inflammation and angiogenesis by producing SASPs such as IL‐1, IL‐6, TNF‐α, and IFN‐γ contributing to creating a tumor‐tolerant microenvironment." (PMID 41427020, 2025). "Finally, silibinin modulates the immune microenvironment by reducing NF-κB-regulated cytokines, such as IL-6, IL-8, and CCL2, which limits TAM recruitment and dampens inflammation-driven tumor growth." (PMID 40650040, 2025). "TAMs promote the EMT of tumor cells by secreting various factors, including TGF-β, IL-6, and CCL2." (PMID 40304000, 2025). "Majorly, IL-6 mobilizes anti-tumor immune response by supporting the activation, expansion, survival, and proliferation of T-cells, increasing CD8+ T-cell trafficking to the tumor site." (PMID 41376623, 2025). "It is widely recognized that mast cells induce neovascularization and angiogenesis by secreting VEGF, FGF-2, PDGF, and IL-6 to the tumor stroma in addition to nonclassical pro-angiogenic drivers such as proteases, particularly tryptases and chymases." (PMID 39858015, 2025). "•SB in the EAC mice model reduced the tumor-specific markers (CEA, TNF-α, IL-6)." (PMID 40712409, 2025). "However, IL6 blockade can “heat up” the TME and shift a “cold” TME to a “hot” one by fine-tuning the immune system towards a more anti-tumor phenotype, thereby enhancing the effectiveness of targeted immunotherapies." (PMID 40427188, 2025). "Research indicates that within specific tumor microenvironments, MSCs can secrete factors including VEGF and IL-6, which may indirectly accelerate tumor progression." (PMID 41301162, 2025). "Tumor sections from mice subjected to Ce6@Lip-TD and Ce6/CpG@Lip-TD with laser treatments exhibited markedly elevated levels of tumor necrosis factor α (TNF-α, red fluorescence) and interleukin 6 (IL-6, green fluorescence) compared to other groups." (PMID 40177379, 2025). "Furthermore, TIM-3 inhibitors suppress IL-6/STAT3 signaling pathway activation in HCC cells, effectively inhibiting tumor proliferation and metastasis, which highlights their therapeutic potential against HCC." (PMID 40980688, 2025). "IL-6 signaling through JAK/STAT3 leads to epithelial-mesenchymal transition (EMT) in oral SCC and stemness of gliomas which may contribute to tumor progression." (PMID 40317079, 2025).
tumor (continued). "Additionally, the EP4 inhibitor suppresses pro-inflammatory cytokine IL-6, chemokine CXCL8, and inflammation-dependent bone metastasis, while alleviating immune suppression and restoring anti-tumor immunity." (PMID 40666730, 2025). "Adenosine can also affect the differentiation of DCs, mainly through binding with A2bRs, so that it can secrete different tumor growth factors in the immune microenvironment of the tumor, including VEGF, IL-6, IL-8, and TGF-β, providing a good “soil” for the growth of tumor cells." (PMID 40420185, 2025). "IL‐6 also recruits MSDCs into the TME and drives EMT, triggering tumor growth and invasiveness." (PMID 39811803, 2025). "IL6 has been shown to downregulate the expression of activating receptors on NK cells, such as NKG2D and NKp30, which impairs their ability to recognize and kill tumor cells." (PMID 40427188, 2025). "The hypothesized clinical relevance is that cisplatin-induced reduction in MSC-derived IL-6, IDO or both could support cancer therapy by removing immunosuppressive factors from the tumor microenvironment." (PMID 40699630, 2025). "However, microglia also secrete critical cytokines such as interferon-γ (IFN- γ), IL-1, and IL-6, alongside chemokines like CCL2 and CXCL10, which modulate T cell activity and recruit immune cells to the tumor site." (PMID 39857798, 2025). "The localization of AKT1 and ESR1 in tumor cells, alongside SRC and IL6 in myeloid cells, highlights potential mechanisms through which the decoction impacts tumor-immune interactions, potentially altering immune surveillance and tumor progression in high-risk locally advanced NPC." (PMID 40746726, 2025). "Furthermore, elevated levels of pro-inflammatory cytokines, such as IL-6 and TNF-α, drive chronic inflammation, creating a favorable environment for tumor cell growth and promoting the angiogenesis necessary for their vascularization." (PMID 39857306, 2025). "More importantly, NETs induce the generation of proinflammatory cytokines such as IL‐8, IL‐6, and TNF‐α, which further increase neutrophil recruitment and NETs formation, thereby promoting tumor immune escape and accelerating the process of metastatic invasion of tumors." (PMID 40979214, 2025). "Both TAMs and M-MDSCs secrete cytokines such as IL-6, IL-10, TGF-β, and vascular endothelial growth factor (VEGF), which promote angiogenesis and immune suppression, thereby contributing to the establishment of a pro-inflammatory tumor microenvironment." (PMID 41440517, 2025). "NE acts on β-adrenergic receptors expressed on TAM and tumor-infiltrating lymphocytes, promoting the secretion of factors such as vascular endothelial growth factor (VEGF) and IL-6, while suppressing CD8+ T cell function and inducing M2 macrophage polarization." (PMID 41142779, 2025). "M1 macrophages play a pivotal anti-tumor role by mediating phagocytosis and antibody-dependent cell cytotoxicity, while releasing pro-inflammatory cytokines such as tumor necrosis factor alpha (TNF-α), interleukin-1β (IL-1β), and interleukin-6 (IL-6)." (PMID 40559655, 2025). "This activation leads to the release of IL-6, TNF-α, and other inflammatory cytokines that enhance neutrophil effector functions, including phagocytosis and ROS production, which contribute to the elimination of tumor cells." (PMID 40486614, 2025). "Our study showed that in cases with high serum IL-6 levels, IL-6 uptake into the tumor is similarly enhanced within TME, and the CD8/CD163 cell ratio in the tumor is reduced, which may present an immunosuppressive microenvironment." (PMID 39652104, 2025). "While these factors are known to mediate pro-angiogenic and tumor-promoting processes in the TME (e.g., IL-6 and IL-8 can upregulate VEGFA expression in tumor cells to drive angiogenesis), analysis of 22Rv1 tumor cells under huB12-MMAE treatment showed no change in VEGFA expression." (PMID 41154598, 2025).
tumor (continued). "Previous research has indicated that IL‐6 upregulates and sustains IDO1 expression in tumor cells, implying that IDO1 may act differently in response to identical signaling stimuli across different cell types." (PMID 40103267, 2025). "It is shown that IL-6 produced by MSCs increases endothelin 1 (ET-1) expression in colorectal cancer (CRC) cells, resulting in the activation of AKT1 and ERK in endothelial cells which lead to tumor neo-angiogenesis enhancement." (PMID 39981232, 2025). "Indeed, large-scale studies have validated the benefit of combining tumor markers such as SCC-Ag and p16 with inflammatory markers (e.g., IL-6, CRP) to improve prognostic accuracy." (PMID 41244922, 2025). "Notably, TGFB1, TGFB2, TGFB3, S100A8, S100A9, IL6, and PTGES secreted by PMN-MDSCs exhibit both protumorigenic and immunosuppressive properties, playing significant roles in promoting tumor growth and evading immune responses." (PMID 41280721, 2025). "Additionally, cytokines such as IL-6, IL-10, and TGF-β (transforming growth factor-β) modulate the activity of the immune system in a way that promotes tumor growth." (PMID 40362280, 2025). "Furthermore, CAFs secreted IL-6, another cytokine enriched in EC TME, drives epithelial-to-mesenchymal (EMT) transition, tumor stemness, and chemoresistance." (PMID 41476608, 2025). "Furthermore, naringenin inhibits the PI3K/Akt/mTOR and IL-6/STAT3 signaling pathways, key oncogenic routes frequently exploited by BPA to drive tumor progression." (PMID 41440754, 2025). "CAAs secrete chemokine ligands CCL2 and CCL5, interleukin-1 (IL-1), interleukin-6 (IL-6), tumor necrosis factor-α (TNF-α), and vascular endothelial growth factor (VEGF), and promote cell aggressiveness, tumor progression, migration, and chemotherapy resistance." (PMID 40141437, 2025). "NB IL-6 and VEGF are the best-characterized cytokines that stimulate tumor growth and metastasis, while others such as IFN-γ may exert anti-NB activity by inducing tumor cell apoptosis and inhibiting angiogenesis." (PMID 40722593, 2025). "The lymphatic endothelial cells (LECs), a component of LVs within the pre-metastatic niche, can be conditioned by tumor-secreted IL-6 to express CCL5 and VEGF, which facilitate C-C chemokine receptor type 5-positive (CCR5+) tumor cell recruitment, extravasation and colonization into the niche." (PMID 40002869, 2025). "Mechanistically, POLR2J4 knockdown reduced the expression of drug resistance genes (ABCB1, ABCC1, BCL2), decreased serum levels of IL-6 and TGF-β1, and downregulated TGF-β1 and PD-L1 in tumor tissues, highlighting its role in establishing an immunosuppressive, drug-resistant microenvironment." (PMID 40661083, 2025). "Collectively, these findings suggest that IL-6 signaling orchestrates a coordinated increase in pro-inflammatory, autophagic, and FOXO-related pathways in NSCLC cells, potentially contributing to tumor cell adaptation and survival mechanisms for cancerous cells under inflammatory conditions." (PMID 41378291, 2025). "A critical outcome of this interaction is the polarization of fibroblasts into inflammatory cancer-associated fibroblasts (iCAFs), which exhibit upregulation of genes including IL-6, SAA1/2, CXCL1, LIF, and αSMA/ACTA2, ultimately contributing to tumor progression." (PMID 39814702, 2025). "Modified MUC1 protein-functionalized AuNPs were found to be potent macrophage activators, promoting the release of IL-6, IL-10, IL-12, and TNF-α from peritoneal macrophages and driving predominant M1 polarization, highlighting their potential as a potent tumor vaccine." (PMID 40801739, 2025). "Secondly, for inhibiting apoptosis, IL-6 activates STAT3 to enhance the expression of anti-apoptotic proteins like Bcl-2 and Bcl-xL, while concurrently repressing pro-apoptotic proteins such as caspase-3, thereby enabling tumor cells to evade apoptosis." (PMID 39980561, 2025).
tumor (continued). "Interaction with host immune cells further accelerates tumor-promoting inflammation: E. coli engages the TLR4/NF-κB signaling axis to induce pro-inflammatory cytokines, including IL-6, IL-8, and TNF-α, which sustain tumor-promoting microenvironments and facilitate angiogenesis." (PMID 41356485, 2025). "For instance, while inhibiting IL-6 or TNF-α may reduce inflammation and tumor growth, it could also compromise the body’s ability to fight infections or control tumor progression." (PMID 40563999, 2025). "IL-6 and IL-8 from chemoresistant CAFs enrich CSCs by creating niches, and IL-32 in CAFs binds integrin β3, activating p38 MAPK signaling, upregulating EMT markers, and promoting tumor invasion." (PMID 40230452, 2025). "First, grade II-III TAM-MGs showed female enrichment of pathways related to anti-tumor inflammatory activity (IFN alpha response, IFN gamma response, and IL6 JAK STAT3 signaling), as well as pathways involved in lipid metabolism (adipogenesis and cholesterol homeostasis)." (PMID 38895459, 2025). "While SASP factors such as IL‐6 and TNF‐α may promote immune cell‐mediated clearance of senescent cells, they could also support tumor progression by fostering a pro‐inflammatory microenvironment." (PMID 40186402, 2025). "In ENKTCL, MDSCs are recruited and activated within the tumor microenvironment (TME) by EBV- and tumor-driven factors, including GM-CSF, IL-6, TGF-β, CCL2, and CXCL8, which promote both monocytic (M-MDSC) and granulocytic (PMN-MDSC) subtypes and enhance their suppressive phenotype." (PMID 41303704, 2025). "Coupled with our data showing that OGP does not effect CT26 proliferation of IL-6 expression (a cytokine essential for CT26 tumor survival in vivo), we found that OGP has the potential to act directly on myeloid cells." (PMID 40307509, 2025). "Compared to the oe‐NC+M2pep‐Cs NPs/Plerixafor group, the mRNA levels of CD80, IL‐1β, and IL‐6 were significantly downregulated, and the mRNA levels of CD206 and IL‐10 were significantly upregulated in the tumor tissues of mice in the oe‐CXCR4+M2pep‐Cs NPs/Plerixafor group." (PMID 40536774, 2025). "Their natural tumor-tropism is a crucial feature of MSCs as drug delivery carriers, with tumor tissues secreting cytokines (like TNF-α, IL-6, and SDF-1) that activate MSC-related signaling pathways (such as PI3K/Akt, MAPK, JAK/STAT), inducing their migration to the tumor microenvironment." (PMID 40142943, 2025). "And M1 macrophages can produce tumor necrosis factor-alpha (TNF-α) and pro-inflammatory cytokines such as IL-6, IL-12, and IL-18, express high levels of Major Histocompatibility Complex Class II (MHC II) and CD68, and inhibit tumor cell growth and proliferation." (PMID 40131539, 2025). "By aligning therapeutic strategies with the tumour’s metabolic-inflammatory landscape, this precision medicine approach goes beyond traditional TNM staging and may improve patient outcomes, IL6." (PMID 41153383, 2025). "Additionally, tumor-derived factors such as PGE2 and IL-6 exacerbate NK cell dysfunction, suppressing IFN-γ secretion and inducing an exhausted NK cell phenotype." (PMID 40534868, 2025). "Importantly, this model is supported by the overlap of pathways: chronic inflammation → IL-6/NF-κB → PI3K/Akt → epithelial–mesenchymal transition (EMT) and tumor invasion, as well as immune evasion." (PMID 41374963, 2025). "Acute IL-6 activation stimulates T cell activation, proliferation, and increased infiltration of CD8+ T cells, enhancing anti-tumor adaptive immunity, tumor cell apoptosis, and inhibiting tumor growth." (PMID 41476977, 2025).